PPM1A (protein phosphatase, Mg2+/Mn2+ dependent 1A)
Diseases named in the same sentence as PPM1A in open-access papers (continued):
Sharing a sentence is not in itself a finding about the gene and the disease.
tumor (21 papers, 2013 to 2026). "PPM1A deficiency is similarly associated with advancing tumor grade and poor prognosis in pancreatic ductal adenocarcinoma (PDAC)." (PMID 29799477, 2018). "Importantly, several tumor tissues, including metastatic human prostate and bladder carcinomas, have shown decreased or loss of PPM1A expression." (PMID 28283039, 2017). "PPM1A expression was strongly associated with the tumor stage (p = 0.038)." (PMID 25026293, 2014). "The study offered the in vitro evidence to properly understand the increase of miR-487a-3p or the decrease of PPM1A as a tumor repressor in OSCC." (PMID 33724144, 2021). "(iv) PPM1A was a member of the protein phosphatase 2C family and an important tumor suppressor, which was involved in regulation of multiple pathways, such as TGFβ/Smad, JNK/p38, Cdk2, Cdk6, and Akt/ERK signaling." (PMID 31920959, 2019). "PPM1A has recently emerged as an important tumor suppressor owing to its involvement in the regulation of several tumor-centric signaling pathways, including TGF-β/smad, Wnt/β-catenin, MAPK, PI3K/Akt, and NF-κB." (PMID 28283039, 2017). "Protein phosphatase magnesium-dependent 1A (PPM1A) has recently emerged as an important tumor suppressor as it can block a range of tumor-centric signaling pathways through protein dephosphorylation." (PMID 28283039, 2017). "Since multiple tumor-related pathways can be modulated by PPM1A, further studies on the exact signaling pathway and its corresponding function in HCC tumorigenesis are needed." (PMID 28283039, 2017). "Compared with the normal liver tissues, significantly lower levels of PPM1A were found in the HCC tumor and adjacent tissues." (PMID 28283039, 2017). "Recently, PPM1a/PP2Cα was found to play a role in wound healing and tumor metastasis by inhibiting TGF-β signal pathway." (PMID 27121309, 2016). "Consistent with our in vitro results, significant reductions in tumor growth and metastasis were observed following PPM1A overexpression." (PMID 25026293, 2014). "Meanwhile, overexpression of PPM1A significantly suppressed tumor growth relative to the growth of T24 PPM1A RNAi cells and vector control cells." (PMID 25026293, 2014). "Moreover, tumor-infiltrating NK cells exhibited the greatest increase in WT group after Ppm1a-depletion." (PMID 40289129, 2025). "Based on the oncogenic roles of PPM1A in OSCC progression, we supposed that miR-487a-3p may serve as a tumor suppressor via targeting PPM1A." (PMID 34336002, 2021). "Investigations have also clarified the essential function of PPM1A in tumor repression." (PMID 33724144, 2021). "The invasive NFPA DEG data demonstrated that the downregulation of PPM1A might contribute to tumor invasion of NFPAs." (PMID 31920959, 2019). "This suggests that PPM1A, a key modulator of the signaling pathway, can be targeted and degraded by more than one hepatitis viral protein, and that this has become one of the strategies of the virus to promote tumor progression." (PMID 28283039, 2017). "This indicates that modulation of the protein level of PPM1A might be an effective strategy for the abnormal activation of the signal pathway in tumor progression." (PMID 28283039, 2017). "Recently, PPM1A has attracted increasing interest owing to its tumor suppressor-like activity." (PMID 28283039, 2017). "Therefore, our findings suggest a notable tumor-promoting role for PPM1A that is dependent on the TGF-β/Smad signaling pathway in BCa." (PMID 25026293, 2014). "However, the expressional regulation and distinct functions of PPM1A in regulating tumor cells remain largely unknown." (PMID 28283039, 2017).
tumor (continued). "However, the distinct functions of PPM1A activity and how PPM1A regulates tumor cell activity remain largely unknown." (PMID 25026293, 2014). "However, how PPM1A regulated during tumor invasion remains to be elucidated." (PMID 25026293, 2014). "This analysis revealed associations with multiple proteins, including SMAD3, RNF14, PPM1A, and OPHN1, implicating PCDH1 in signaling cascades relevant to tumor progression and stemness regulation." (PMID 41602375, 2026). "PPM1A also controls nerve growth factor-activated Akt/ERK, tumor proliferation, migration, and cell invasion." (PMID 33724144, 2021). "Importantly, several tumor tissues, including HCC, showed decreased or loss of PPM1a expression, indicating that uncovering the regulatory mechanisms of PPM1a expression might be useful for explaining the aberrant status of TGF-β signal pathway in tumor development." (PMID 27121309, 2016). "The correlations between PPM1A and biomarkers related to the TGF-β signaling pathway and tumor invasion were also detected in BCa samples." (PMID 25026293, 2014). "In conclusion, the study demonstrated that miR-487a-3p might act as a tumor suppressor by inhibiting the growth and invasion of OSCC via regulating PPM1A expression." (PMID 33724144, 2021). "Compared to normal liver tissues, the expression of PPM1A was significantly decreased in the HCC tumor tissues and adjacent non-tumor tissues." (PMID 28283039, 2017). "Tumors were considered negative for PPM1A expression when there was no nuclear staining or staining in < 5% of the tumor cells (n = 46), positive staining in ≥ 5% of the neoplastic cells was considered nuclear staining (n = 99)." (PMID 25026293, 2014). "Furthermore, in xenograft tumors formed from T24 PPM1A RNAi cells, the tumor margin was not continuous and was even absent in most cases; as a result, these tumors were more likely to infiltrate into the surrounding tissue (p < 0.05)." (PMID 25026293, 2014). "Notably, Ppm1a depletion suppressed tumor growth only in WT group but not S58A group." (PMID 40289129, 2025). "However, in ER-negative cells where PPM1A expression is low, CDKs are not dephosphorylated, and the phosphorylated form of CDK6 phosphorylates RB, which causes the release of E2F, allowing it to bind DNA and induce transcription of E2F-regulated genes, ultimately stimulating tumor growth." (PMID 31372497, 2019). "Besides, the correlation between the miR-181c overexpression after -and possibly induced by- the MAP treatment and the absence of the tumor relapse, can be partially explained considering that among its putative targets figure genes regulating the cell cycle, like GATA6, MAP2K1, PPM1A and Notch2." (PMID 26062442, 2015).
infection (10 papers, 2012 to 2026). The state of being infected such as from the introduction of a foreign agent such as serum, vaccine, antigenic substance or organism. "Intriguingly, using a Citrobacter rodentium murine infection model, we found that NleD can enhance intestinal colonization in a manner independent of its protease activity, possibly via interaction with PPM1A." (PMID 41902461, 2026). "The results showed that PPM1A abundance was significantly reduced within 2–3 days of infection with JFH1, and the PPM1A level at 5 days after infection was approximately 30% that of uninfected cells as indicated by the immunoblots." (PMID 28283039, 2017). "In extension, achievable HIV-1 WEAU infection levels of THP-PPM1A-KD cells were found reduced when compared to infection of naïve THP-1 cells, a result consistent with the idea that PPM1A would control the innate antiviral response of macrophages." (PMID 27004401, 2016). "In this study, we describe that infection with either pathogen up-regulated the expression of Protein Phosphatase, Mg2+/Mn2+ Dependent 1A (PPM1A), which we identify as a molecule that directly links the antiviral and the antibacterial response of macrophages." (PMID 27004401, 2016). "In HeLa cells, overexpression of PPM1A inhibited infection of a HIV-1 reporter virus and also suppressed gene expression of a HIV-1 reporter plasmid." (PMID 22727189, 2012). "PPM1A upregulation thus seems to be a key factor for Mtb to establish a persistent infection in macrophages, by hijacking the innate immune response of its host cells, and disabling the natural ability of macrophages to undergo apoptosis in response to pathogen infection." (PMID 28176854, 2017). "We hypothesized that the reduction in PPM1A abundance might be mediated by one or more viral proteins expressed during infection." (PMID 28283039, 2017). "PPM1A mRNA was upregulated in HCV-infected cells from 2 days after infection." (PMID 28283039, 2017). "Mtb-infection induced regulation of PPM1A expression should be of general interest to research on bacterial infections, as we here demonstrate that PPM1A up-regulation not only subverts the cellular innate antiviral response of macrophages, but also drives macrophages into an immune paralyzed state." (PMID 27004401, 2016). "This would establish the idea that HIV-1 (or for that matter other viruses) could have evolved a viral escape mechanism that would inactivate the innate antiviral response in macrophages by infection-induced up-regulation of PPM1A." (PMID 27004401, 2016). "Over a range of viral input levels, PPM1A overexpression tripled the achievable infection levels." (PMID 27004401, 2016). "Indeed, anisomycin, a reported JNK phosphorylation agonist could counteract the PPM1A upregulation enforced suppression of JNK phosphorylation following Mtb-infection, and restored the ability of macrophages to undergo apoptosis in response to Mtb infection." (PMID 28176854, 2017). "We found that phosphorylation of TBK1 in TRIM18 KO BMDM was significantly enhanced relative to that in WT BMDM after infection with CVB3 or adenovirus, suggesting that TRIM18 indeed recruited PPM1A to dephosphorylate TBK1 for TBK1 inactivation." (PMID 35909127, 2022). "In this scenario, PPM1A overexpressing cells retained higher cell viability relative to parental THP-1 cells (57% vs. 16%), as assessed by flow cytometry on day 2 post infection." (PMID 28176854, 2017). "In either case, correlating with an infection rate of 56% or 70% for HIV-1 NL43 or WEAU, respectively, a ∼2-fold increase in PPM1A protein levels was observed 24 h post infection." (PMID 27004401, 2016). "Similarly, Listeria monocytogenes directly hijacks PPM1A and PPM1B to dephosphorylate and translocate SIRT2 into the nucleus to promote effective infection." (PMID 33882943, 2021).
infection (continued). "The results using this method confirmed that PPM1A overexpression indeed inhibited Mtb-induced THP-1 cell apoptosis, as indicated by 4-fold reduction in active caspase-3/7 in the samples from THP-PPM1A cells on day 2 post-infection." (PMID 28176854, 2017). "Consistent with a potential role of PPM1A in the control of cellular antiviral response, infection with HIV-GFP vectors, over a wide range of infection levels, resulted in two-fold higher levels of active infection events in THP-PPM1A cells than in THP-1 control cells." (PMID 27004401, 2016).
metabolic disease (2 papers, 2020 to 2023). A congenital disorder (due to inherited enzyme abnormality) or acquired (due to failure of a metabolically important organ) disorder resulting from an abnormal metabolic process. "Together, we highlight that PPM1A may represent a therapeutic target for metabolic diseases in many aspects, such as increasing anti-inflammatory responses and enhancing the secretion of insulin-sensitizing adipokines which depends on dephosphorylation of PPARγ at Ser273." (PMID 32024237, 2020).
adenocarcinoma (1 paper, 2021). A common cancer characterized by the presence of malignant glandular cells. "We also employed small interfering RNAs (siRNAs) to deplete the endogenous expression of PPM1A in HEK293, human adenocarcinoma alveolar basal epithelial A549, and immortalized human normal keratinocyte HaCaT cells." (PMID 33630828, 2021).
neurodegenerative disease (1 paper, 2012). A disorder of the central nervous system characterized by gradual and progressive loss of neural tissue and neurologic function. "By affecting the PI3K/AKT pathway PPM1A might be engaged in regulating these cellular responses and thus may play a role in neurodegenerative diseases." (PMID 22384250, 2012). "In concert with earlier studies on the involvement of PPM1A and PPM1B in neurodegeneration and neuroprotection PPM1A is probably required during embryonic development of the central neuronal system (CNS) and may participate in neuronal death in neurodegenerative diseases." (PMID 22384250, 2012).
PPM1A also shares sentences with these, for which no sentence is quoted: rheumatoid arthritis (2 papers); type 2 diabetes (2); acute myeloid leukemia (1); bacterial infections (1); breast tumors (1); cardiovascular disease (1); diabetes (1); head and neck cancer (1); herpes simplex encephalitis (1); kidney diseases (1); metastatic tumors (1); non-alcoholic fatty liver disease (1); peripheral neuropathy (1); pneumonia (1); stomach adenocarcinoma (1); synovitis (1).